TTF1 (transcription termination factor 1)
Diseases named in the same sentence as TTF1 in open-access papers (continued):
Sharing a sentence is not in itself a finding about the gene and the disease.
adenocarcinoma (continued). "Key immunohistochemical markers, including CK20, CDX2, and TTF‐1, play a pivotal role in distinguishing PEAC from other adenocarcinomas." (PMID 39980580, 2025). "Immunohistochemical (IHC) analysis showed positivity for pan-CK, TTF-1, CK7, and NapsinA, and negativity for P40 and P63, consistent with adenocarcinoma." (PMID 40054123, 2025). "SCC usually lacks expression of CK7, while adenocarcinomas are CK7-positive, often with co-expression of TTF-1 and napsin A. A CK7−/p40+ profile strongly supports SCC, whereas CK7+/TTF-1+ suggests glandular origin." (PMID 40427131, 2025). "As evident from the figures, the adenocarcinoma cell lines retained their expression profiles with positive CK7 and positive CK7 and TTF-1, respectively, in all culturing methods." (PMID 39441367, 2024). "Regarding the adenocarcinoma cell lines, NCI-H1975 was positive for both TTF-1 and CK7, while A549 and A110L were positive only for CK7." (PMID 39441367, 2024). "Immunohistochemically, adenocarcinoma cells were positive for 34βE12, CAM5.2, TTF-1 clone SPT24 and 8G7G3/1, napsin A, SP-A, and CEA." (PMID 35144634, 2022). "Biomarkers that are most commonly used for this purpose include mesothelial (calretinin, D2-40, WT1 and cytokeratin 5/6), epithelial (Claudin 4), and adenocarcinoma markers (Ber-EP4, TTF-1, CEA, MOC31, Napsin A)." (PMID 36292206, 2022). "Whether IMA exhibited NKX2‐1/TTF‐1 exon 1 expression was further validated using qPCR, revealing that 19 of 20 (95%) cases exhibited higher exon 1 expression relative to that of exon 4/5, compared to EGFR‐mutated adenocarcinoma that was immunohistochemically positive for TTF‐1." (PMID 34014042, 2021). "Haematoxylin and eosin (HE) staining of the primary surgically resected tumour sample revealed typical adenocarcinoma histology with positive IHC markers including Napsin A, cytokeratin 7 (CK7), thyroid transcription factor‐1 (TTF‐1) and ALK (Ventana)." (PMID 34541785, 2021). "He underwent biopsy of one liver lesion, and pathology demonstrated poorly differentiated adenocarcinoma with focal neuroendocrine differentiation (CK7+, CDX2+, synaptophysin/chromogranin+, CK20−, TTF1−, napsin−) consistent with pancreatic or biliary origin." (PMID 31371345, 2019). "In patients with adenocarcinoma CK7 in 100% of patients (13 patients), TTF1 in 61.5% of patients (8 patients) and CEA in 53.8% of patients (7 patients) were positive, but HBME1 and Calretinin were negative for all patients." (PMID 31528168, 2019). "Finally, the Adenocarcinoma factor shows association with the RNA expression of a number of keratins, negative coefficients for both copy number and RNA expression of SOX2 and positive association with both RNA expression and copy number of NKX2-1 (also known as TTF1)." (PMID 30379847, 2018). "In the current classification, a solid carcinoma without glandular structures or mucin production, but with immunohistochemical positivity for “adenocarcinoma markers”, i.e., TTF-1 (NKX2-1) and/or Napsin A, is diagnosed as an adenocarcinoma." (PMID 29538329, 2018). "Given her smoking history, imaging characteristics, and the TTF-1 and cytokeratin 7 (CK7) positivity of her staining pattern, the diagnosis is consistent with an adenocarcinoma of pulmonary origin." (PMID 29900025, 2017). "In conclusion, our data indicate that CD73 and A2AR are more commonly expressed in adenocarcinoma, particularly TTF-1-positive and mutant EGFR-positive adenocarcinoma." (PMID 28060732, 2017).
adenocarcinoma (continued). "Among adenocarcinomas, significantly higher CD73 and A2AR expression was observed in TTF-1-positive and mutant EGFR-positive tumors than in their counterparts." (PMID 28060732, 2017). "We also immunohistochemically evaluated TTF-1 expression and found that the combination of MUC5B with TTF-1 is a useful marker for adenocarcinomas." (PMID 25733373, 2015). "Thyroid transcription factor-1 (TTF-1) is a marker of TRU-type adenocarcinoma, and two studies concerning 11 and 12 ALK-positive patients each revealed TTF-1 positivity in all ALK-positive adenocarcinomas." (PMID 24885886, 2014). "Overexpression of TTF-1 mRNA was found only in 3 (30%) of 10 NSCLC cell lines, including 1 (25%) of 4 adenocarcinoma cell lines." (PMID 22940844, 2012). "The TTF-1 expression was found at a very low frequency in NSCLC cell lines, including adenocarcinoma cell lines." (PMID 22940844, 2012). "The negative rate of TTF-1 in mucus-producing adenocarcinomas was significantly higher than that in non-mucus-producing adenocarcinomas (18/29 [62.1%] vs. 18/63 [28.6%]; p < 0.01)." (PMID 42266151, 2026). "Although some nuclei showed PTC-like chromatin clearing, negative staining for TTF1 and GATA3 and the absence of KRAS/NRAS mutations ruled out mesonephric-like adenocarcinoma." (PMID 40959354, 2025). "The LAC and LAC-TB groups expressed adenocarcinoma markers TTF-1 and Napsin A, along with CK and CK7, but lacked CD56, P40, and CK5/6 expression." (PMID 40061944, 2025). "Bronchoscopy with biopsy confirmed metastatic lung adenocarcinoma, with histopathology showing moderately differentiated adenocarcinoma, positive for TTF-1 and Napsin A and negative for PAX8." (PMID 40708867, 2025). "The cells were positive for CK7 and TTF-1 and negative for p40, likely representing fragments of a poorly differentiated adenocarcinoma​." (PMID 40827171, 2025). "Immunohistochemistry was positive for Napsin A and thyroid transcription factor-1 (TTF-1) and negative for cytokeratin (CK) 5/6, p40, synaptophysin, and chromogranin A, consistent with adenocarcinoma." (PMID 40385873, 2025). "The squamous cell lines included in the further analyses (HCC-95 and HCC-1588) were also stained for the markers commonly expressed in adenocarcinomas (CK7 and TTF-1) and the selected adenocarcinoma cell lines (NCI-H1975 and A549) were stained for squamous markers (p40 and CK5)." (PMID 39441367, 2024). "Both PDO69 and PDO62 derived from surgical resections for adenocarcinoma and thus are expected to be positive for pan-CK and TTF-1 and negative for p40." (PMID 39796658, 2024). "The immunostaining for TTF1 alone does not distinguish between pulmonary adenocarcinomas and adenocarcinomas of non-pulmonary origin because ~75–80% of them are TTF1-positive." (PMID 39329988, 2024). "Biopsy of the transverse colon tumor confirmed a poorly differentiated adenocarcinoma, which was positive for CK-7 and TTF-1, very focally positive for napsin A, but negative for CK-20 and CDX-2." (PMID 39292398, 2024). "Biopsy revealed a poorly differentiated adenocarcinoma positive for CK-7 and TTF-1, very focally positive for napsin A, and negative for CK-20 and CDX-2." (PMID 39292398, 2024). "Tumors exhibiting coarse granular cytoplasmic positivity for napsin A, nuclear positivity for TTF-1, and negative staining for p63 were diagnosed as adenocarcinomas." (PMID 39070322, 2024). "In our study, we did not encounter double positivity with TTF-1 and p63, but the literature suggests that focal p63 coexpression can be seen in cases of adenocarcinoma." (PMID 39070322, 2024). "The patient underwent complete surgical resection of the BM in November 2018, reporting a CK7 positive, CK20 and TTF-1 negative adenocarcinoma consistent with the primary pancreatic origin." (PMID 38260832, 2023). "Immunohistochemical staining confirmed the diagnosis of adenocarcinoma positive for TTF-1 and cytokeratin (CK) 7 and negative for p63 and CK5/6." (PMID 35029172, 2022).
adenocarcinoma (continued). "Subgroup analyses of large clinical trials (JMDB, PointBreak, PRONOUNCE) using regimens with PEM have reported lower efficacy in TTF-1-negative adenocarcinomas (NOS)." (PMID 36614938, 2022). "First, nonsq NSCLC cases that are TTF-1-positive are more likely to be adenocarcinoma in comparison to those that are TTF-1-negative." (PMID 36614938, 2022). "Mesonephric-like adenocarcinomas are characterized by the expression of GATA3 or TTF1 with the absence of ER/PR expression." (PMID 35053578, 2022). "In conclusion, a combination of at least two positive mesothelial (calretinin, CK 5/6, WT-1 and D2-40) and at least two negative adenocarcinoma immunohistochemical markers (TTF1, CEA and Ber-EP4) should be used in the differential diagnosis of MPM." (PMID 36557076, 2022). "An extirpation was performed via frontotemporal access, revealing likely metastasis of a poorly differentiated, TTF-1-negative adenocarcinoma." (PMID 35448155, 2022). "Immunohistochemical testing showed that the adenocarcinoma components were positive for TTF-1, Napsin A, and CK7 and negative for CK5/6 and p40." (PMID 33602172, 2021). "Cells of the adenocarcinoma component were CAM.5.2, CK7, CK AE1/AE3, and GATA-3 positive and negative for synaptophysin, chromogranin A, parathormone, parafibromin, thyroglobulin, TTF1, calcitonin, glucagon, S100, PGP-9 and Bcl-2." (PMID 32506375, 2021). "Pathology showed adenocarcinoma immunohistochemically consistent with lung primary (TTF-1 positive, Napsin A positive, CK7 positive, CK20 negative, synaptophysin negative, chromogranin negative)." (PMID 32560187, 2020). "In 8 patients (61.5%) with adenocarcinoma TTF1 was positive, but was negative for all patients (7 patients) with MPM." (PMID 31528168, 2019). "Thirty-nine patients (97.5%) had adenocarcinoma and one patient (2.5%) had thyroid transcription factor-1 (TTF-1) negative NSCLC." (PMID 31380273, 2019). "Immunohistochemically, nonmucinous MIA tumors are TRU-type adenocarcinomas that stain positive for pneumocyte markers TTF-1 and Napsin A, which is an aspartic proteinase involved in the maturation of surfactant protein B in type II pneumocytes." (PMID 29690599, 2018). "LG1 and LG50 as adenocarcinoma were tested by the clinical indexes (CK8/18, NapsinA, and TTF1)." (PMID 29788985, 2018). "All adenocarcinomas were positive for CK7 and most of them (18/20; 90%) were positive for TTF-1." (PMID 29531543, 2017). "Moreover, we further investigated chemotherapeutic efficacy of stage IB adenocarcinomas between TTF-1− group and TTF-1+ group." (PMID 29296178, 2017). "Negative TTF-1 staining had a very strong negative predictive value (all except one patient had TTF-1 positive adenocarcinoma)." (PMID 25264519, 2014). "Our data also clearly indicated that EGFR mutations are more likely to occur in TTF-1 positive tumors (145/675; 17.7%) than in TTF-1 negative adenocarcinomas (3/218; 1.4%)." (PMID 23934203, 2013). "Although our study did not compare the histological findings of SqCC and adenocarcinoma, no SqCC reacted with Napsin A, and only a few cases of SqCC showed weak reaction for TTF-1." (PMID 24069587, 2013). "The TTF1-negative adenocarcinomas derive from the centrally-based cells: the bronchial basal and the mucous cells." (PMID 23224985, 2013). "With respect to TTF-1, its expression did not reduce dramatically in intermediate- and high-grade adenocarcinomas." (PMID 21811254, 2011). "A possible explanation is that TTF-1-negative adenocarcinomas are often less differentiated and may harbor molecular or immunologic features that evade immune surveillance, regardless of PD-L1 level." (PMID 40647486, 2025). "TTF-1 expression was observed in 33 of 35 adenocarcinoma cases, while 2 cases were negative." (PMID 40746930, 2025).
adenocarcinoma (continued). "Additionally, non-squamous and non-adeno NSCLCs are associated with a poorer prognosis than adenocarcinoma, suggesting that TTF-1 negative NSCLC has a biologically inferior prognosis compared to TTF-1 positive NSCLC." (PMID 39076994, 2024). "Morphologically, the ciliated adenocarcinoma in this case appeared to be a non-TRU type adenocarcinoma, with partial mucous epithelium, no visible extracellular mucus, thyroid transcription factor (TTF)-1 negativity, and mucin (MUC) 5AC positivity on immunostaining." (PMID 38860177, 2024). "Furthermore, the histological tumor type was moderately to poorly differentiated adenocarcinoma positive for CK-7 and TTF-1, very focally positive for napsin A, but negative for CK-20 and CDX-2." (PMID 39292398, 2024). "In conclusion, we found that the positivity of TTF‐1 expression was associated with PD‐L1 expression status, and that adenocarcinoma patients with positive TTF‐1 expression showed better ORR and PFS than those with negative TTF‐1 expression when treated with ICI monotherapy." (PMID 35808895, 2022). "Although this study excluded cases in which TTF-1 immunostaining had not been performed in patients diagnosed with adenocarcinoma in HE staining, the response of these patients to platinum-doublet chemotherapy was very similar to that of patients who were TTF-1-positive." (PMID 36614938, 2022). "The TTF1 was also negative allowing to eliminate an adenocarcinoma." (PMID 31692820, 2019). "Anti-Napsin A expression may help to identify a small fraction of these TTF1-negative adenocarcinomas." (PMID 29881714, 2018). "Thus, we undertook an investigation of TTF-1 expression in stage I adenocarcinoma and compared the chemotherapeutic effect between TTF-1 positive adenocarcinoma and TTF-1 negative adenocarcinoma in pathological stage IB patients." (PMID 29296178, 2017). "Our meta-analysis of available evidence suggests that TTF-1 can accurately predict whether an adenocarcinoma cell originated from a pulmonary or non-pulmonary site." (PMID 26806377, 2016). "In this context, the adenocarcinomas are characterized with expression of CK14, transcription factor Nkx2.1 (TTF1), CCSP, and SPC and arose from the BADJ in murine model, suggesting that club cells or AEC II cells stem/progenitor cells may be the initiating cells for adenocarcinomas in distal lung." (PMID 25810726, 2015). "In almost all other organs except thyroid, adenocarcinomas are negative for TTF-1." (PMID 26705222, 2015). "In our study, TTF-1 expression was negative in only 10 adenocarcinoma cases." (PMID 24743427, 2014). "Moreover, lesions did not stain with antibodies against the adenocarcinoma subtype marker TTF1." (PMID 34870316, 2022). "Subsequently, cytology analysis identified adenocarcinoma cells from the PE, a re-biopsy turned out to be adenocarcinoma of the enlarged lesion (cT4N3M1c, stage IV), and immunohistochemistry findings showed that the tumor cells were positive for TTF-1 and NapsinA and negative for CK5/6." (PMID 33663050, 2021). "For example, a lung cancer biopsy showing “carcinoma” on the H&E section is typically stained for a set of markers to determine whether it is best classified as adenocarcinoma or squamous carcinoma, as most adenocarcinomas will be positive for TTF1 and NapsinA, but negative for p63, and vice versa." (PMID 34386519, 2021). "In addition, no TTF-1-positive stromal cells could be observed in adenocarcinoma portion of mass by immunohistochemical staining." (PMID 21599956, 2011). "However, in the present case, adenocarcinoma portion and PSH portion were separated distribution without gradual transition area under the microscopical examination by serial section, and there was no TTF-1 positive round cells found in the fibroblastic stroma of adenocarcinoma." (PMID 21599956, 2011).
adenocarcinoma (continued). "The initial pathological report indicated adenocarcinoma, supported by immunohistochemical staining positive for CK7, TTF‐1, and Napsin‐A, and negative for CK20, CDX‐2, GATA‐3, and PAX‐8." (PMID 41415017, 2025). "Here, a panel including CK7, TTF-1, and napsin A is critical: these markers are generally absent in SCC but positive in adenocarcinomas, especially of lung origin." (PMID 40427131, 2025). "CT‐guided core biopsy with IHC suggested adenocarcinoma (CK7, TTF‐1, Napsin‐A positive), but PET‐CT showed no metastasis." (PMID 41415017, 2025). "TTF-1 is expressed in 60–90% of LUAD patients and thyroid carcinomas but is typically absent in adenocarcinomas of other sites and NSCLC squamous cell carcinomas as detected by immunohistochemistry (IHC)." (PMID 39630375, 2025). "All eight initially diagnosed adenocarcinomas that were tested for TTF-1 were positive for TTF-1 (n = 8, 100%), and in one adenocarcinoma patient, TTF-1 was not performed." (PMID 35268520, 2022). "In particular, SWI/SNF interacts with the transcription factor NK2 homeobox 1 (NKX2.1/TTF-1) in CRPC-NE cells, but not in adenocarcinoma cells." (PMID 33144576, 2020). "Biopsy of the large mediastinal showed poorly differentiated adenocarcinoma that stained positive for CK7 but negative for CDX2, TTF‐1, NapsinA, and CK 20, consistent with an ampullary origin." (PMID 31102323, 2019). "Further immunohistochemical profiling showed that this BML3 was positive for CEA (Carcinoembryonic antigen usually positive in adenocarcinoma) and CK7 but was negative for TTF1, Napsin A and PSA." (PMID 31416169, 2019). "In contrast, mucinous AIS rarely expresses TTF-1 protein; therefore, a majority of mucinous AIS tumors are considered non-TRU-type adenocarcinomas." (PMID 29690599, 2018). "Microscopically, the hernia sac was diffusely infiltrated by moderately differentiated adenocarcinoma, which was positive for CK7 and pancytokeratin and negative for TTF-1, CK20, PSA, and CDX2." (PMID 30009070, 2018). "In total, 2813 stage I patients including 126 adenocarcinomas with negative TTF-1 expression and 2687 adenocarcinomas with positive TTF-1 expression were subjected to the study." (PMID 29296178, 2017). "Lung biopsy revealed a poorly differentiated adenocarcinoma with immunohistochemistry (IHC) positive for CEA, CK20, CDX2, and negative for CK7, TTF-1, Napsin A, synaptophysin, and chromogranin." (PMID 27171493, 2016). "All adenocarcinoma showed strong staining for TTF-1, except for two: ADi10 and ADi13 were negative for TTF-1." (PMID 26000095, 2015). "In other cases, the results of ΔNP63 (P40) and 34βE12 were negative but positive for TTF-1 and CK7, and the cases should be diagnosed as poorly differentiated adenocarcinoma." (PMID 25886585, 2015). "A small transbronchial biopsy of the pulmonary infiltrate showed a histology and immunohistochemistry (IHC) profile (mucin stain+, CK7+, TTF1+, CK5/6-, p63-) of primary adenocarcinoma (data not shown)." (PMID 24279718, 2013). "Ovaries were normal, but the adnexal biopsy disclosed an adenocarcinoma positive for CK7, CK8, CK19, CA125, and PR and negative for CK20, CEA, TTF1, CA19-9 and vimentin." (PMID 23758919, 2013). "A scrotal skin biopsy revealed a poorly-differentiated adenocarcinoma, immunohistochemically positive for cytokeratin 7 (CK7) and for thyroid transcription factor 1 (TTF-1), and negative for CK20." (PMID 18801198, 2008). "However, adenocarcinoma is generally positive for CEA, TTF-1, and napsin A and negative for calretinin and vimentin, whereas in MM, the scenario is reversed." (PMID 38938650, 2024). "This study excluded adenocarcinoma patients whose TTF‐1 expression status was unknown; this could be a selection bias as TTF‐1 would be measured when morphological features of adenocarcinoma were not apparent." (PMID 35808895, 2022).
adenocarcinoma (continued). "Moreover, research on the prognosis of patients with TTF-1–negative, EGFR-positive adenocarcinoma is also limited." (PMID 31196060, 2019).